PLAG1 (PLAG1 zinc finger)
Diseases named in the same sentence as PLAG1 in open-access papers (continued):
Sharing a sentence is not in itself a finding about the gene and the disease.
tumor (45 papers, 2008 to 2025). "Given the role of PLAG1 in malignant tumors, the association of PLAG1 with different tumor types has been rarely studied." (PMID 40276502, 2025). "Rearrangements of the PLAG1 gene, and/or overexpression, are associated with benign tumors and neoplasia in different tissues." (PMID 38586898, 2024). "To validate the tumor-specific features of each tumoroid, we assessed the expression of PLAG1, which are representative diagnostic markers of PA46." (PMID 35672412, 2022). "Consistent with their roles as oncogenes, Plag1 and Plagl2 promote proliferation, anchorage-independent growth, loss of contact inhibition and tumor formation in mice." (PMID 30361413, 2018). "Through analysis of the association between the PLAG1 expression and clinic-pathological characteristics, we determined that the positive PLAG1 expression was associated with larger tumor size (P = 0.030)." (PMID 25060425, 2014). "Tumor invasiveness, miR-26a, and PLAG1 expression could be used as survival risk factors." (PMID 34885097, 2021). "The reason for the difference in classifier scores for PLAG1-fused tumors remains to be investigated, but inclusion of this tumor group in future iterations of the reference database will hopefully help their prospective accurate identification." (PMID 40751809, 2025). "Based on data from TCGA, we found that PLAG1 was significantly upregulated in eight types of tumor tissues compared to normal tissues." (PMID 40276502, 2025). "The relationship between PLAG1 expression and tumor heterogeneity, stemness and immune infiltration was investigated." (PMID 40276502, 2025). "In summary, we describe a third subtype of PLAG family-altered pediatric CNS embryonal tumor characterized by PLAG1 gene fusion, which leads to upregulation of PLAG1 and downstream genes." (PMID 40751809, 2025). "We examined the correlation between PLAG1 expression and tumor heterogeneity by analyzing six indicators." (PMID 40276502, 2025). "The fact that the identical gene set also shows high expression in PLAG1-fused tumors, supports the classification of these three subtypes into a single overarching tumor entity." (PMID 40751809, 2025). "Pleiomorphic Adenoma Gene 1 (PLAG1) is a transcription factor that plays a role in diverse biological processes such as tumor progression, cell redox homeostasis, and ferroptosis, emerging as a potential target for cancer research and therapy." (PMID 40403492, 2025). "Our results highlight the prognostic relevance of PLAG1 in various tumor types, indicating its potential as a biomarker." (PMID 40276502, 2025). "We delved deeper into examining the relationship between PLAG1 expression levels and tumor heterogeneity and stemness." (PMID 40276502, 2025). "On the other hand, PLAG1 is involved in tumor progression by regulating downstream pathways such as IGF2 and Wnt, which are closely related to tumorigenesis in various solid malignancies." (PMID 40276502, 2025). "We describe a novel subtype of CNS embryonal tumor with PLAG1 gene fusion that is driven by upregulation and subsequent overexpression of wild-type PLAG1 through promoter hijacking." (PMID 40751809, 2025). "Our results showed that sorafenib had a higher efficacy in reducing tumor volume in MHCC97H/sh-PLAG1 cells than the control group." (PMID 38745179, 2024). "According to the IHC scoring, the levels of PLAG1 in tumor tissues were significantly higher compared to those in peritumoral tissues." (PMID 38745179, 2024). "Fluorescence in situ hybridization (FISH) for PLAG1(8q12) break-apart was performed on tumor cells, which revealed PLAG1 gene break-apart in 63% of the tumor cells (break-apart rate was greater than the 15% threshold)." (PMID 39479012, 2024). "Most of these recent developments were represented by diverse recurrent oncogene fusions as driver events in distinct subsets of neoplasms of well established (endometrial stromal) origin or of ambiguous (PLAG1, NTRK fusions and others) histogenetic origin." (PMID 39196362, 2024).
tumor (continued). "The effectiveness of Sorafenib in inhibiting tumor growth was assessed in subcutaneous and orthotopic mouse models, in conjunction with PLAG1 level reduction." (PMID 38745179, 2024). "We observed significant upregulation of PLAG1 in tumor (4-fold, p < 0.01) and normal slices (4.6-fold, p < 0.001) at long-term culture." (PMID 35884847, 2022). "The Plag gene family has three members; Plagl1/Zac1, which is a tumor suppressor gene, and Plag1 and Plagl2, which are proto-oncogenes." (PMID 30361413, 2018). "Plag1 and Egr1 gene transcript levels were assessed by realtime quantitative PCR with cDNA extracted from CD44hi and CD44neg tumor cells." (PMID 21858056, 2011). "The 12 tumours with PLAG1 mRNA expression showed higher levels of P4-specific IGF2 transcripts (P=0.01) and tended to show higher levels of P3-specific IGF2 transcripts (P=0.051) than the 8 tumours without PLAG1 expression." (PMID 19034281, 2008). "In this study, HB tumours with PLAG1 mRNA expression showed and tended to show higher levels of P4 and P3 transcripts, respectively." (PMID 19034281, 2008). "Hence, we aimed to conduct a more detailed investigation of this elusive and potentially novel rare tumor (sub-)type and therefore screened for more tumors with PLAG1 alterations in this set of 143,827 samples." (PMID 40751809, 2025). "Furthermore, among the 11 tumor types analyzed, the PLAG1 mRNA expression shows a significant correlation with age, with 4 tumor types exhibiting a positive correlation and 7 showing a negative correlation." (PMID 40276502, 2025). "This implies that PLAG1 may be subject to epigenetic regulation during tumor development, highlighting its potential as a predictive marker for clinical staging." (PMID 40276502, 2025). "However, across 15 tumors, there was a significant correlation between tumor purity with PLAG1 expression." (PMID 40276502, 2025). "Therefore, we performed a systematic pan-cancer analysis of PLAG1, aiming to explore its expression pattern, genetic alterations in different tumor types and its relationship with clinical prognosis." (PMID 40276502, 2025). "The prognostic value of PLAG1 was investigated by analyzing tumor DFS and PFI." (PMID 40276502, 2025). "Given that HMGA2 and PLAG1 rearrangements have been described in other neoplasms with epithelial-myoepithelial differentiation, in particular in PAs, we sought to define whether AMEs may harbor fusion genes known to underpin PAs." (PMID 30675516, 2019). "Thus, our data reveal that the tumor-suppressive functions of Ezh2 are to maintain repression of a small number of oncogenes, including Plag1 and potentially Lin28b, which, upon derepression, contribute to more rapid AML development." (PMID 30890554, 2019). "One tumor harbored NKTR-PLAG1, where PLAG1 was fused with intron 10 of the inverted NKTR gene." (PMID 29084941, 2017). "Consequently, the tumor cells were found to be positive for PLAG1 IHC and demonstrated PLAG1 rearrangement on FISH." (PMID 26943407, 2015). "miR-21 has been described as an oncogene, plays a role in enhancing tumor phenotypes including proliferation and migration, and has been shown to target a number of key regulators of these processes, including but not limited to PLAG1 and PTEN." (PMID 21698265, 2011). "PLAG1 mRNA was highly expressed in most HB tumours compared with normal liver tissues." (PMID 19034281, 2008). "PLAG1 positive co-expressed genes were mainly enriched in macroautophagy and respiratory electron transport chain, suggesting that PLAG1 may promote tumor cell survival by regulating autophagy and mitochondrial metabolism, which may also affect BLCA drug resistance." (PMID 40276502, 2025). "For example, the tumor-driving H3.3K27M mutation in pediatric diffuse intrinsic pontine gliomas (DIPGs) results in the inactivation of the PRC2 complex, causing ectopic expression of LIN28B, PLAG1, and PLAGL1, and leading to the de-differentiation and hyperproliferation of tumor cells." (PMID 27588417, 2016).
tumor (continued). "Indeed, Igf2 isa direct target gene of the transcription factor PLAG1, which plays an important role in the tumorigenic process, since genetic ablation of Igf2 in the PLAG1 transgenic mouse model significantly delayed the tumor formation." (PMID 26167473, 2015). "In addition, our study also highlights the correlation of age with PLAG1 expression, aging is considered an important factor in tumorigenesis, and the accumulation of DNA damage and increased levels of inflammation create a favorable environment for tumor cells to evade immune surveillance." (PMID 40276502, 2025). "In the assessment of tumor stemness, a notable positive correlation was found between PLAG1 expression levels in LGG and GBMLGG and all six types of tumor stemness." (PMID 40276502, 2025). "In order to establish a correlation between PLAG1 and GPX4, IHC analysis was performed on a total of 139 samples of tumor and peritumoral tissues obtained from the HCC patient cohort." (PMID 38745179, 2024). "Significant change of expression, reaching 10- to 58-fold change between uterine lesion compared to non-tumor counterpart, was observed in CAPN6, CD24, HMGA1, PLAG1, SNORA48, and SNORD10 (upregulation) and DKK3 and STK26 (downregulation)." (PMID 37466765, 2024). "Expression of PLAG1, which is a partner gene of the detected CHCHD7-PLAG1 fusion gene, was strongly upregulated in the tumor (log2 ratio, 4.2)." (PMID 32702887, 2020). "Recent data on three other lncRNAs (miR-181a/135a/302c) showed that all of them function as tumor suppressors, repressing PLAG1/IGF2 signaling, and exert their effect on 5-fluorouracil (5-FU) chemoresistance through attenuation of PLAG1 expression." (PMID 31623387, 2019). "Strikingly, a mixed control group of 12 benign and malignant PLAG1-altered neoplasms showed no immunohistochemical staining for MDM2." (PMID 40338436, 2025). "As discussed for the PLAGL1/2-amplified tumors, the classification of PLAG1-fused tumors as an embryonal tumor should not automatically imply a specific treatment regimen." (PMID 40751809, 2025). "In contrast to the nuclear positivity for PLAG1 (clone 3B7) observed in a pleomorphic adenoma, which served as a positive control, the tumor cells were completely negative." (PMID 41230282, 2025). "Mirkovic and Fletcher reported that six cases of LLT of the vulva showed immunohistochemical loss of pRB but no expression of PLAG1, suggesting a relationship with the SCL tumor family." (PMID 41230282, 2025). "Seven of the twelve PLAG1-fused samples received a Heidelberg classifier (v12.8) calibrated score above 0.9 for CNS embryonal tumors with PLAGL amplification (ET, PLAGL) indicating their belonging to that tumor type." (PMID 40751809, 2025). "Regarding MATH, it was observed that PLAG1 mRNA expression had a negative correlation with 2 tumor types." (PMID 40276502, 2025). "Interestingly, 52% of tumor tissue samples with decreased PLAG1 levels also showed reduced GPX4 levels, whereas 79% of samples with increased PLAG1 levels showed elevated GPX4 expression." (PMID 38745179, 2024). "In the absence of PLAG1 gene rearrangement, and/or overexpression of PLAG1, PLAG1 protein can have antiproliferative activity and tumor suppression." (PMID 38586898, 2024). "Additionally, the tumor-suppressive functions of EZH2 are to maintain repression of a small number of oncogenes, including pleiomorphic adenoma gene 1 (Plag1) and potentially Lin28b, which, upon derepression, will accelerate the development of AML." (PMID 39655332, 2024). "On the other hand, detection of any fusion gene, or any PLAG1 fusion gene, did not correlate with survival or tumor stage at diagnosis in these patients." (PMID 29084941, 2017). "Further analysis of immune-stimulating factors revealed that in tumors such as LGG, PRAD, and BRCA, the expression of PLAG1 was significantly positively correlated with immune-stimulating factors like CD48, CD27, and TMIGD2, which may enhance anti-tumor immune responses." (PMID 40276502, 2025).
tumor (continued). "Furthermore, we found that patients with positive KPNA2 and positive PLAG1expression (KpPp) in tumor have the poorest RFS and OS compared to other groups, suggesting the combination of high KPNA2 and PLAG1 density in nucleus would add accuracy to predict the prognosis of HCC patients." (PMID 25060425, 2014). "As a cancer-promoting gene, PLAG1 plays an essential role in the processes of adenocarcinoma formation and malignant transformation in various types of tumors, whereas PDCD4 is a tumor suppressor gene that inhibits neoplastic transformation and tumor cell invasion and facilitates apoptosis." (PMID 21192833, 2010). "PLAG1 positively regulates IGF2, and its expression was detected in 12 tumours, foetal liver RNA and 2 cell lines, but not in 8 tumour and 3 normal liver tissues." (PMID 19034281, 2008). "Immunohistochemical staining indicated that the tumor cells were positive for murine double minute 2 (MDM2) and cyclin-dependent kinase 4 (CDK4), and negative for pleomorphic adenoma gene 1 (PLAG1)." (PMID 39109289, 2024).
cancer (33 papers, 2010 to 2025). A tumor composed of atypical neoplastic, often pleomorphic cells that invade other tissues. "Our study indicates that the expression levels of PLAG1 across various cancer types are associated with multiple immune-related genes." (PMID 40276502, 2025). "PLAG1, a gene located on chromosome 8q12, consists of 5 exons and has been linked to cancer-related activities such as proliferation, migration, and invasion." (PMID 38745179, 2024). "Rearrangements of the PLAG1 gene, and/or overexpression, are associated with benign tumors and cancers in a variety of tissues." (PMID 38586898, 2024). "The overexpression of PLAG1 later in life is typically associated with the formation of solid tumors and cancers." (PMID 38586898, 2024). "KPNA2 could affect carcinogenesis by mistaken translocation of cancer-associated cargo proteins such as c-Myc and PLAG1, both of which could be found in the liver-specific KPNA2 PPI network." (PMID 34616632, 2021). "PLAG1 has the potential to be a prognostic marker and a potential therapeutic target for patients with malignant tumors." (PMID 40276502, 2025). "Later, studies have also explored the relationship between PLAG1 and malignant tumors, and found that its expression is related to the invasiveness and prognosis of a variety of malignant tumors, including LIHC, KIRC and invasive pituitary adenoma." (PMID 40276502, 2025). "Secondly, our conclusions still need to be verified by in vitro and in vivo experiments to confirm the role of PLAG1 in cancer progression and immune regulation." (PMID 40276502, 2025). "Pleomorphic adenoma gene 1 (PLAG1) can be detected in both pleomorphic adenoma and carcinoma ex pleomorphic adenoma." (PMID 40326164, 2025). "PLAG1 stimulates the IGF2 gene and excess production of IGF2 is considered one mechanism linked to tumors and cancers." (PMID 38586898, 2024). "The autocrine pathway would constantly supply the PI3K/AKT signal cascade, contributing to IGF-2 overexpression through a positive feedback loop mediated by PLAG1, as demonstrated in some benign and malignant tumors." (PMID 36901760, 2023). "On the contrary, in malignant cases like carcinoma ex pleomorphic adenoma markers Plag-1, CK7, and P63 were used." (PMID 38021816, 2023). "The WES also allowed us to identify CNV-seq in 42 cancer-associated genes with cn > 3, including NOTCH1, MYC, NUMA1, PLAG1, and RAD21 amplified in 10% of tumors." (PMID 35884575, 2022). "The CNV analysis by sequencing (CNV-seq) revealed five cancer-associated genes as the most frequent with gains (NOTCH1, MYC, NUMA1, PLAG1, and RAD21), while 30% of the tumors showed SMARCA4 with loss." (PMID 35884575, 2022). "Among them, five cancer-associated genes were confirmed by both analyses as the most frequent genes with gains: NOTCH1, MYC, NUMA1, PLAG1, and RAD21." (PMID 35884575, 2022). "The fetal transcription factor PLAG1 is found to be overexpressed in cancers, and has been suggested to bind the insulin like growth factor 2 (IGF2) P3 promoter, and to activate the IGF2 gene." (PMID 23023303, 2012). "We also assessed the promoter methylation levels of PLAG1 across different cancer types." (PMID 40276502, 2025). "This suggests that PLAG1 may influence the response of cancer cells to specific targeted therapies or chemotherapy agents." (PMID 40276502, 2025). "Twenty years ago, some studies pointed out that abnormal expression of PLAG1 may lead to uncontrolled cell proliferation, which was consistent with the mechanism of the occurrence of a variety of malignant tumors." (PMID 40276502, 2025). "PLAG1 has the potential to be a prognostic marker and a therapeutic target for cancer patients." (PMID 40276502, 2025). "The literature on the role of pleomorphic adenoma gene 1 (PLAG1) in malignant tumors is limited." (PMID 40276502, 2025).
cancer (continued). "The differential expression and prognosis of PLAG1 were analyzed based on TCGA pan-cancer data." (PMID 40276502, 2025). "In short, this suggests that PLAG1 plays a significant role in regulating cellular death and could provide insight into new cancer treatment strategies." (PMID 38745179, 2024). "Whilst insulin-like growth factor 2 (Igf2) is an experimentally validated gene across numerous developmental and cancer contexts, it remains unclear if PLAG1 regulates Igf2 expression in the embryonic cortex." (PMID 38240991, 2024). "Pleomorphic adenoma gene 1 (PLAG1) is a transcription factor involved in cancer and growth." (PMID 31182756, 2019). "The misexpression of Plag1 in these cancers is due to chromosomal translocations that place Plag1 under the control of regulatory elements for ubiquitously expressed genes, such as Elongation factor SII gene (Tcea1), Ctnnb1 (β-catenin) and Leukemia inhibitory factor receptor (Lifr)." (PMID 30361413, 2018). "Also, researchers have illustrated that the activation of PLAG1 is considered to play important roles in the pathogenesis of various types of cancers." (PMID 25060425, 2014). "Our findings suggest a new role for PLAG1 in IGF2 overexpression in cancer." (PMID 23023303, 2012). "In addition to known roles in cancer, PLAG1 is also a critical developmental factor." (PMID 38240991, 2024). "Our analysis reveals a significant correlation between PLAG1 and DFS as well as PFI across multiple cancer types." (PMID 40276502, 2025). "Both PLAG1 and PLAGL2 overexpression in cultured cells triggers IGF2 gene expression and induces cancer-promoting effects, including transformation." (PMID 37371750, 2023). "Two members in the family, PLAG1 and PLAGL2, were found to be cell growth promoting and oncogenic in several cancer cell types." (PMID 32087738, 2020). "PLAG1 also drives cancer metastasis via its transcriptional regulation of isocitrate dehydrogenase (NADP)-specific glutamate dehydrogenase 1 (Gdh1), mediating anti-anoikis and pro-metastatic signalling within cancer cells." (PMID 38240991, 2024). "Notably, in some benign and malignant tumors, IGF2 expression is directly regulated by Pleomorphic adenoma gene 1 (PLAG1), inducing autocrine IGF-1R signaling that leads to the activation of PI3K/AKT downstream cascade, enhancing cell survival and proliferation." (PMID 36901760, 2023).
benign tumors (2 papers, 2024 to 2025). "Hence, the regulated expression of PLAG1 is associated with normal cellular function in different tissues, while overexpression is linked with benign tumors and malignancies." (PMID 38586898, 2024).